NUSAP1 (nucleolar and spindle associated protein 1)
Diseases named in the same sentence as NUSAP1 in open-access papers (continued):
Sharing a sentence is not in itself a finding about the gene and the disease.
astrocytoma (continued). "Further, ectopic expression or knockdown of NUSAP1 significantly promoted or inhibited, respectively, the invasive ability of astrocytoma cells." (PMID 28899410, 2017). "With regard to its molecular mechanism, upregulation of NUSAP1 in astrocytoma cells promoted the nuclear translocation of GLI family zinc finger 1 (GLI1) and upregulated the downstream genes of the Hedgehog pathway." (PMID 28899410, 2017). "Taken together, our findings provided evidence for the role of NUSAP1 in the progression of astrocytoma and the potential of NUSAP1 as a prognostic biomarker as well as target in astrocytoma treatment." (PMID 28899410, 2017). "Our findings indicated that NUSAP1 played an important role in promoting aggressiveness in astrocytoma via activating the HH pathway." (PMID 28899410, 2017). "In conclusion, our study revealed that NUSAP1 plays an important role in astrocytoma progression by promoting the proliferation, invasion and migration of tumor cells." (PMID 28899410, 2017). "Subsequently, the SW 1088 and U-87 MG cell lines, which stably overexpressed and suppressed NUSAP1 expression, respectively, were stereotactically implanted into the brain of nude mice; there was also a control group in which a control astrocytoma cell line was implanted." (PMID 28899410, 2017). "Moreover, NUSAP1 promoted the invasive ability of astrocytoma cells both under in vitro and in vivo conditions." (PMID 28899410, 2017). "Moreover, intracranial xenografts of astrocytoma cells engineered to express NUSAP1 were highly invasive compared with the parental cells." (PMID 28899410, 2017). "As the expression of NUSAP1 was upregulated in astrocytoma, we further investigated whether there was a correlation between NUSAP1 expression and survival." (PMID 28899410, 2017). "NUSAP1 contributes to the progression of astrocytoma by enhancing tumor cell invasiveness via activation of the Hedgehog signaling pathway, and that NUSAP1 might be a potential prognostic biomarker as well as a target in astrocytoma." (PMID 28899410, 2017). "To investigate whether NUSAP1 has an effect on the pathogenesis of astrocytoma, we used gene set enrichment analysis (GSEA) to predict the possible biological functions of NUSAP1 in the cancer." (PMID 28899410, 2017). "Thus, our data indicated that the expression of NUSAP1 was upregulated in astrocytoma cell lines and tissues." (PMID 28899410, 2017). "NUSAP1 expression was found to be upregulated in astrocytoma compared to normal brain tissues." (PMID 28899410, 2017). "The 3-(4, 5-dimethyl-2-thiazolyl)-2,5-diphenyl-2H-tetrazolium bromide (MTT) assay showed that the NUSAP1-transduced astrocytoma cells (SW 1088 and A172 cells) displayed a significant increase in viability, while the NUSAP1-silenced U-87 MG and A172 cells displayed contrasting results." (PMID 28899410, 2017). "Furthermore, the level of NUSAP1 was notably positively related to poor overall survival in astrocytoma patients." (PMID 28899410, 2017). "To further confirm these results obtained from public datasets, we examined the expression of NUSAP1 in two normal brain tissues, eight astrocytoma tissues, one primary normal human astrocyte (NHA) cell line and seven astrocytoma cell lines by real-time PCR and western blotting." (PMID 28899410, 2017). "Thus, NUSAP1 might be a useful prognostic biomarker and a potential target in the diagnosis and treatment of astrocytoma." (PMID 28899410, 2017). "Interestingly, GSEA analysis revealed that the expression level of NUSAP1 in TCGA astrocytoma dataset was positively correlated with the HH pathway gene signature, further suggested that NUSAP1 may play a role in activation of HH pathway." (PMID 28899410, 2017). "Thus, the findings indicate that NUSAP1 promotes aggressiveness in astrocytoma in vivo." (PMID 28899410, 2017). "Thus, NUSAP1 might be a potential prognostic biomarker as well as a treatment target in astrocytoma." (PMID 28899410, 2017).
astrocytoma (continued). "However, although a number of studies have explored the role of NUSAP1 in various tumors, its role in astrocytoma remains unknown." (PMID 28899410, 2017). "Our data indicated that NUSAP1 promoted GLI1 translocation to the nucleus from the cytoplasm and subsequently led to activation of the HH signaling pathway in astrocytoma cells." (PMID 28899410, 2017). "NUSAP1 also upregulated the expression of the downstream targets of HH pathway including PTCH1, HIP1, CCND1, CCNE1 and HDAC1 in astrocytoma." (PMID 28899410, 2017). "With regard to the molecular mechanism, we found that upregulation of NUSAP1 promoted the translocation of GLI1 from the cytoplasm to the nucleus and upregulated the downstream genes of the HH pathway in astrocytoma cells." (PMID 28899410, 2017). "NUSAP1 promotes the nuclear translocation of GLI family zinc finger 1 and activates the Hedgehog signaling pathway, resulting in increased aggressiveness of astrocytoma." (PMID 35739489, 2022). "In addition, NUSAP1 has been shown to promote metastasis by activating WNT signaling pathways in cervical cancer, triple-negative breast cancer, and nasopharyngeal carcinoma, and Hedgehog signaling in astrocytoma." (PMID 37047232, 2023).
bladder cancer (9 papers, 2020 to 2024). "Nuclear and spindle-associated protein 1 (NUSAP1) has been shown to promote bladder cancer progression through the TGF-β signaling pathway, and its expression is also associated with lymph node metastasis and survival prognosis." (PMID 39285476, 2024). "Moreover, in bladder cancer, nucleolar and spindle associated protein 1 (NUSAP1) was upregulated, and its expression was closely related to the poor prognosis of patients, which was also demonstrated to regulate EMT via the TGF-β signaling pathway, as well as p-Smad2/3 and vimentin expression." (PMID 32456355, 2020). "PrognoScan online analysis showed that the overall survival rate of bladder cancer patients with high NUSAP1 expression was significantly shorter than that of patients with low NUSAP1 expression ((p < 0.001)." (PMID 35487972, 2022). "According to reports, silencing NUSAP1 inhibited proliferation, migration, and invasion of bladder cancer cells." (PMID 35710427, 2022). "Nucleolar and spindle associated protein 1 (NUSAP1) facilitates proliferation, migration, invasion and EMT of bladder cancer cells via the activation of the TGF-β signaling." (PMID 34818994, 2021). "In addition, O-GlcNAcylation in bladder cancer can promote NUSAP1 expression, and in turn enhance the proliferation and inhibit apoptosis in bladder cancer HT-1376 and T24 cells." (PMID 35487972, 2022). "Moreover, by activating the TGF-β signaling pathway, NUSAP1 can enhance the proliferation, migration, invasion, and chemotherapy resistance of bladder cancer cells." (PMID 35483343, 2022). "Similarly, a high NUSAP1 expression level facilitated the development of bladder cancer by regulating epithelial-mesenchymal transition of bladder cancer via the TGF-β signaling pathway." (PMID 33927744, 2021). "The protein stability of NUSAP1 decreases after knocking down OGT expression in HT-1376 and T24 cells to reduce O-GlcNAcylation, thus promoting bladder cancer cell apoptosis." (PMID 39285476, 2024).
pancreatic ductal adenocarcinoma (9 papers, 2020 to 2025). An infiltrating adenocarcinoma that arises from the epithelial cells of the pancreas. "In pancreatic ductal adenocarcinoma, Nucleolar and spindle associated protein 1 (NUSAP1) lactylation at H3K18 activates mitotic spindle assembly checkpoint regulator TTK and BUB1B, which further promotes glycolysis and lactate accumulation in tumor cells." (PMID 40421024, 2025). "Lysine lactylation of nucleolar and spindle-associated protein 1 (NUSAP1) by CBP/p300 in pancreatic ductal adenocarcinoma (PDAC) enhances its association with the LDHA promoter, hence increasing LDHA expression." (PMID 40755753, 2025). "Lactylation of nucleolar and spindle‐associated protein 1 (NUSAP1) inhibits its degradation, upregulating NUSAP1 expression and promoting the metastasis of pancreatic ductal adenocarcinoma." (PMID 40443721, 2025). "In oncological studies, nucleolar- and spindle-associated protein 1-mediated lactylation, in conjunction with lactate dehydrogenase A, forms a positive feedback loop that promotes pancreatic ductal adenocarcinoma metastasis." (PMID 38291438, 2024). "Nucleolar and spindle associated protein 1 (NUSAP1), a microtubule-associated protein, played an important role in metastasis of pancreatic ductal adenocarcinoma (PDAC) by regulating LDHA-mediated glycolysis." (PMID 39502530, 2024). "NUSAP1 serves as a pivotal oncogenic factor in pancreatic ductal adenocarcinoma, driving proliferation, migration, and epithelial-mesenchymal transition, while inhibiting the AMPK signaling pathway." (PMID 39100078, 2024).
lymph node metastasis (6 papers, 2019 to 2023). "In BUC, NUSAP1 showed high expression and was significantly associated with lymph node metastasis, pathological stage, pathological grade, and tumor diameter." (PMID 35487972, 2022). "The level of NUSAP1 expression was an independent risk factor for lymph node metastasis in BUC (p < 0.05)." (PMID 35487972, 2022). "Overexpression of NUSAP1 is associated with lymph node metastasis and recurrence of PTC." (PMID 35710427, 2022). "Compared to the NUSAP1 low expression group, the NUSAP1 high expression group was more likely to also have lymph node metastasis, pathological PTC type, shorter progression-free survival (PFS), and higher scores for immune checkpoint inhibitor treatment." (PMID 35710427, 2022). "The present study also showed that NUSAP1 was an independent predictor of lymph node metastasis in BUC." (PMID 35487972, 2022). "NUSAP1 was an independent predictor of lymph node metastasis and prognosis in BUC; higher expression indicated poorer prognosis of BUC patients." (PMID 35487972, 2022). "Correlation analysis showed that high expression of NUSAP1 positively and significantly correlated with lymph node metastasis in patients." (PMID 30678687, 2019). "Lymph node metastasis was significantly correlated with pathological stage, pathological grade, tumor number, tumor diameter, and NUSAP1 expression (p < 0.05); only NUSAP1 expression was an independent predictor of lymph node metastasis in BUC (OR:1.786, 95% CI 1.229–2.596, p = 0.002)." (PMID 35487972, 2022). "In addition, NUSAP1 was an independent predictor for lymph node metastasis and BUC." (PMID 35487972, 2022). "In addition, patients with high NUSAP1 expression are more likely to develop lymph node metastasis, and these patients primarily have typical pathological types of PTC, which further illustrates the potential of NUSAP1 to serve as a prognostic marker." (PMID 35710427, 2022). "Additionally, patients with high NUSAP1 expression in KICH, KIRC, KIRP, LUAD, LUSC, PARD and SKCM were more prone to lymph node metastasis (N status), and NUSAP1 levels positively correlated with distant metastases (M status) in patients with KIRC, KIRP, LIHC, and LUAD." (PMID 37781040, 2023). "High expression of NUSAP1 in BUC was not significantly related to the patient’s gender, age, or tumor number (p > 0.05), however was significantly associated with pathological grade, tumor diameter, pathological stage, and lymph node metastasis (p < 0.05)." (PMID 35487972, 2022). "However, NUSAP1 level was not significantly correlated with tumor grade, lymph node metastasis, residual tumor size, or pathological type." (PMID 35739489, 2022).
oral squamous cell carcinoma (6 papers, 2015 to 2022). "In oral squamous cell carcinoma, NUSAP1 downregulation enhances the anti-tumor effect of paclitaxel by activating apoptotic pathways." (PMID 35739489, 2022). "Okamoto demonstrated that inhibition of NUSAP1 suppressed tumor proliferation and enhanced the anti-tumor effect of paclitaxel by activating apoptotic pathways in oral squamous cell carcinoma." (PMID 30678687, 2019). "The aim of this study was to reveal functional mechanisms of NUSAP1 in oral squamous cell carcinoma (OSCC)." (PMID 26554377, 2015). "In addition, NUSAP1 knockdown has been observed to potentiate paclitaxel-induced apoptosis in oral squamous cell carcinoma." (PMID 36478748, 2022). "Further, NUSAP1 could be a biomarker of oral squamous cell carcinoma, as it was reported that downregulation of NUSAP1 suppressed tumor proliferation and enhanced the anti-tumor effect of paclitaxel." (PMID 28899410, 2017).
triple-negative breast carcinoma (6 papers, 2019 to 2025). An invasive breast carcinoma which is negative for expression of estrogen receptor (ER), progesterone receptor (PR), and human epidermal growth factor receptor 2 (HER2). "Remarkably, overexpression of NUSAP1 (HR = 4.136, 95% CI = 1.956-8.747, P < 0.001) was identified as an independent prognostic indicator of disease-free survival in triple-negative breast cancer." (PMID 32226503, 2020). "NUSAP1 expression was correlated with BRCA1, BRCA2, and BARD1 expression, and upregulation of NUSAP1 predicted poor prognosis in triple-negative breast cancer." (PMID 30678687, 2019). "In triple-negative breast cancer, the expression level of NUSAP1 was found to be significantly correlated with BRCA1 expression and higher expression of NUSAP1 led to poor prognosis while positive BRCA1 was related to improved outcomes." (PMID 31729978, 2019). "In this study, NUSAP1 depletion is found to significantly increases the proliferation, migration, and invasion of triple-negative breast cancer (TNBC) cells in vitro and promotes TNBC progression in vivo, suggesting that NUSAP1 is a tumor suppressor in TNBC." (PMID 41178464, 2025). "The combination of NUSAP1 and BRCA1 improves the prognostic power in triple-negative breast cancer compared with the calculation based on age, menstrual status, and lymph node status." (PMID 35739489, 2022).
colon cancer (5 papers, 2020 to 2022). "In addition, Liu reports that the mRNA and protein levels of NUSAP1 were more highly expressed in colon cancer than in paired non-cancerous adjacent tissues." (PMID 33927744, 2021).
lung adenocarcinoma (5 papers, 2013 to 2025). A carcinoma that arises from the lung and is characterized by the presence of malignant glandular epithelial cells. "While NUSAP1's association with various tumors is established, its predictive value for prognosis and immunotherapy in lung adenocarcinoma (LUAD) remains unconfirmed." (PMID 39781524, 2025). "In a previous study, MEF2D was demonstrated to enhance the proliferation and metastasis of lung adenocarcinoma cells A549 and H1299 by promoting the transcription of NUSAP1." (PMID 37653017, 2023). "However, the specific regulatory mechanisms and potential targeting therapies of NUSAP1 in lung adenocarcinoma (LUAD) remain largely elusive." (PMID 39430250, 2024). "The results showed that NUSAP1 was related to five cancers; prostate adenocarcinoma (PRAD), kidney chromophobe (KICH), kidney renal papillary cell carcinoma (KIRP), liver hepatocellular carcinoma (LIHC), and lung adenocarcinoma (LUAD) were associated with shorter OS." (PMID 35710427, 2022).
lung cancer (5 papers, 2020 to 2025). A malignant neoplasm involving the lung. "For example, in lung cancer, tumor-derived lactate promotes the nuclear translocation of nucleolar and spindle associated protein 1 (NUSAP1) and the transcriptional activity of DESMIN in CAFs, thereby driving their activation." (PMID 41152975, 2025). "In lung cancer, lactate induces the nuclear translocation of nucleolar and spindle-associated protein 1 (NUSAP1) in fibroblasts, which facilitates JUNB-FRA1-FRA2 transcriptional complex binding to the DESMIN promoter, ultimately upregulating CAF markers (DESMIN, TGFB1, SDF1)." (PMID 40565047, 2025). "High expression of NUSAP1 is positively correlated with poor prognosis in lung cancer and cervical carcinoma." (PMID 33489890, 2020). "It is indicated that NUSAP1 knockdown inhibited cell growth and metastasis via regulating BTG2/PI3K/AKT signaling in nonsmall-cell lung cancer." (PMID 34782617, 2021).
renal cell carcinoma (5 papers, 2020 to 2024). "Conversely, it was also discovered that silence of NUSAP1 resulted in G2/M arrest of renal cell carcinoma (RCC) cells." (PMID 34782617, 2021).
Cirrhosis (4 papers, 2019 to 2024). A chronic disorder of the liver in which liver tissue becomes scarred and is partially replaced by regenerative nodules and fibrotic tissue resulting in loss of liver function. "Hence, TOP2A, PRC1, and NUSAP1 have the potential to be liver biopsy-based markers for screening HCC high-risk patients with cirrhosis." (PMID 31001331, 2019). "It is concluded that BUB1B, NUSAP1, TTK, HMMR, CCNA2, and KIF2C can be considered as potential novel molecular indicators for the onset and development of HCC, since they are linked to the transition from cirrhosis to HCC." (PMID 36199789, 2022). "Additionally, our validation datasets revealed that NUSAP1 expression was higher in CHB patients with inflammation and cirrhosis." (PMID 38441732, 2024).
osteosarcoma (4 papers, 2020 to 2024). A usually aggressive malignant bone-forming mesenchymal neoplasm, predominantly affecting adolescents and young adults. "This study aims to reveal that hypoxia promotes the invasion of osteosarcoma cells by up-regulating the expression of NUSAP1." (PMID 34322597, 2021). "In this study, we found that hypoxia can promote the migration and invasion of osteosarcoma cells by up-regulating the expression of NUSAP1." (PMID 34322597, 2021). "We investigated the effects of hypoxia on the expression of NUSAP1 in human osteosarcoma cell line MG63." (PMID 34322597, 2021). "We reported for the first time the role of NUSAP1 in osteosarcoma, which is consistent with its role in other types of tumors." (PMID 34322597, 2021). "Finally, decreased expression of NUSAP1 seems to sensitize osteosarcoma cells to paclitaxel, as NUSAP1 interacts with the RanBP2-RanGAP1-UBC9 SUMO E3 ligase complex, allowing for accurate chromosomal segregation." (PMID 36478748, 2022). "HIF-1α and NUSAP1 were valuable targets for the treatment of osteosarcoma." (PMID 34322597, 2021). "We speculated that NUSAP1 was the downstream target of HIF-1α transcriptional regulation and participates in the regulation of osteosarcoma cell migration and invasion in a HIF-1α-dependent manner." (PMID 34322597, 2021). "However, the role of NUSAP1 in the hypoxia response of osteosarcoma has not been reported." (PMID 34322597, 2021).
acute myeloid leukemia (3 papers, 2020 to 2024). Acute myeloid leukemia (AML) is a group of neoplasms arising from precursor cells committed to the myeloid cell-line differentiation. "Intriguingly, study has reported that NUSAP1 may influence immune responses through its interaction with DNA or RNA and implicated in the proliferation of acute myeloid leukemia (AML) cells." (PMID 39430250, 2024). "NUSAP1 expression in acute myeloid leukemia can block the cell cycle, whereas reduction in the NUSAP1 expression increased the killing effect of paclitaxel on oral epithelial squamous cell carcinoma cells." (PMID 32420375, 2020). "Also, NUSAP1 plays a role as a tumor antigen in acute myeloid leukemia (AML), and studies have confirmed that the production of its specific antibody is related to the sustained remission of the disease, and the detection of NUSAP1 antibody is beneficial to monitor the progression of AML." (PMID 36982952, 2023).